SEPHS1 (selenophosphate synthetase 1)
Diseases named in the same sentence as SEPHS1 in open-access papers:
SEPHS1 is named in the same sentence as 37 diseases in open-access papers, as found by Europe PMC text mining. Sharing a sentence is not in itself a finding about the gene and the disease. The quoted sentences say what the papers report.
embryonal carcinoma (2 papers, 2021). A non-seminomatous malignant germ cell tumor characterized by the presence of large germ cells with abundant cytoplasm resembling epithelial cells, geographic necrosis, high mitotic activity, and pseudoglandular and pseudopapillary structures formation. "Recently it was reported that H2O2 was accumulated in Sephs1-knockout, F9, embryonic carcinoma cells." (PMID 34769076, 2021). "Depletion of SEPHS1 in mouse embryonal carcinoma cells reduces the expression of glutathione system proteins, compromises the redox homeostasis and reverses some of the malignant phenotypes, suggesting that SEPHS1 may be involved in tumorigenesis." (PMID 33622411, 2021).
hepatocellular carcinoma (2 papers, 2021 to 2025). A malignant tumor that arises from hepatocytes. "A recent pan-cancer study further demonstrated that SEPHS1 expression was broadly associated with tumor immunity and patient prognosis, showing favorable outcomes in low-grade glioma but poorer survival in hepatocellular carcinoma." (PMID 41441975, 2025). "Furthermore, SEPHS1 has been included in a nine-gene risk model based on amino acid metabolism in hepatocellular carcinoma." (PMID 41441975, 2025). "Silencing of Sephs1 reduced tumor cell proliferation, migration and invasion, consistent with reports that identified SEPHS1 as a driver of metastasis in hepatocellular carcinoma via the TGF-β/SMAD pathway." (PMID 41441975, 2025).
liver cancer (2 papers, 2021 to 2025). An epithelial or non-epithelial malignant neoplasm that arises from the liver. "SEPHS1 displayed a dual prognostic role, acting as protective in gliomas and hematological malignancies but adverse in liver cancer and melanoma, suggesting tumor-specific functions." (PMID 41441975, 2025). "Selenophosphate synthetase 1 (SEPHS1) promotes the expression of SMADs in liver cancer cells and stimulates the migration and invasion of tumors induced by TGF-β, which is negatively correlated with the OS and RFS of HCC patients." (PMID 34557495, 2021).
osteoarthritis (2 papers, 2022 to 2025). A noninflammatory degenerative joint disease occurring chiefly in older persons, characterized by degeneration of the articular cartilage, hypertrophy of bone at the margins and changes in the synovial membrane. "For example, in osteoarthritis, downregulation of SEPHS1 impairs selenoprotein synthesis in chondrocytes, leading to reduced antioxidant capacity and cartilage degeneration." (PMID 41441975, 2025).
acute lymphoblastic leukemia (1 paper, 2025). Leukemia with an acute onset, characterized by the presence of lymphoblasts in the bone marrow and the peripheral blood. "SEPHS1 showed the highest expression in acute lymphoblastic leukemia and neuroblastoma, and the lowest expression in chronic myeloid leukemia and chronic lymphocytic leukemia." (PMID 41441975, 2025).
adrenocortical carcinoma (1 paper, 2025). "Specifically, elevated SEPHS1 expression was associated with reduced OS in adrenocortical carcinoma (HR = 3.462, p < 0.001), liver hepatocellular carcinoma (HR = 2.598, p < 0.001), and skin cutaneous melanoma (HR = 1.503, p < 0.001)." (PMID 41441975, 2025). "In addition, SEPHS1 expression showed strong positive correlations with tumor mutational burden in selected cancers, including adrenocortical carcinoma, lung adenocarcinoma, and melanoma." (PMID 41441975, 2025).
bladder cancer (1 paper, 2025). "In contrast, in bladder cancer, high SEPHS1 expression is associated with increased tumor mutational burden, elevated PD-L1 expression, and improved immunotherapy response, possibly due to enhanced neoantigen release." (PMID 41441975, 2025). "In melanoma, its inhibition was associated with enhanced immune infiltration and improved response to PD-1 blockade in preclinical models, whereas in bladder cancer, high SEPHS1 expression may be associated with a more immunogenic phenotype and improved response to checkpoint blockade." (PMID 41441975, 2025).
bladder urothelial carcinoma (1 paper, 2025). "cBioPortal analysis showed that SEPHS1 exhibited modest alteration alteration frequencies in uterine corpus endometrial carcinoma and bladder urothelial carcinoma, mainly due to point mutations and copy number amplification, respectively." (PMID 41441975, 2025).
colon cancer (1 paper, 2025). "At the protein level, data from the CPTAC showed that SEPHS1 protein expression was significantly elevated in colon cancer, ovarian cancer, and glioblastoma compared to adjacent normal tissues, mirroring its mRNA expression pattern." (PMID 41441975, 2025).
Crohn disease (1 paper, 2015). A gastrointestinal disorder characterized by chronic inflammation involving all layers of the intestinal wall, noncaseating granulomas affecting the intestinal wall and regional lymph nodes, and transmural fibrosis. "In a Caucasian population from New Zealand, where the soil is poor in Se and Se intake is low, rs7901303 and rs17529609 in selenophosphate synthetase 1 (SEPHS1) and rs1553153 in Sec tRNA synthase (SEPSECS) were significantly associated with Crohn’s Disease." (PMID 25988760, 2015).
embryonic cancer (1 paper, 2021). "Malignant properties, including cell invasion and foci formation, were inhibited by SEPHS1 deficiency in F9 cells, which are a mouse embryonic cancer cell line." (PMID 34769076, 2021). "Unlike in other cell lines, such as the embryonic cancer F9 cell line in which SEPHS1 expression was ablated, knockout of Sephs1 in 2H11 cells led to a morphological change from a fibroblast-like shape to a spindle shape with long, thin cytoplasm." (PMID 34769076, 2021).
gastric adenocarcinoma (1 paper, 2025). "Previous studies reported SEPHS1 overexpression in gastrointestinal malignancies such as rectal and gastric adenocarcinomas." (PMID 41441975, 2025).
lung carcinoma (1 paper, 2025). "High SEPHS1 expression was consistently associated with elevated chromosomal instability in bladder, breast, and lung cancers." (PMID 41441975, 2025).
melanoma (1 paper, 2025). A malignant, usually aggressive tumor composed of atypical, neoplastic melanocytes. "In melanoma, high SEPHS1 expression was linked to reduced CD8+ T cell infiltration and activation of immunosuppressive pathways." (PMID 41441975, 2025). "Overall, these results indicate that SEPHS1 promotes immune evasion by limiting chemokine signaling and antigen presentation, and its inhibition can enhance antitumor immune responses in melanoma." (PMID 41441975, 2025). "This study identifies SEPHS1 as a critical immunometabolic regulator that contributes to immune evasion in melanoma." (PMID 41441975, 2025). "To investigate how SEPHS1 shapes the immunosuppressive landscape in melanoma, we analyzed transcriptomic profiles from the TCGA-SKCM cohort." (PMID 41441975, 2025). "SEPHS1 was further investigated in melanoma through in vitro and in vivo experiments, including gene knockdown, T cell co-culture, flow cytometry, and transcriptomic profiling." (PMID 41441975, 2025). "In melanoma, silencing Sephs1 enhanced CD8+ T cell infiltration and improved the efficacy of anti-PD-1 therapy." (PMID 41441975, 2025). "SEPHS1 promotes immune evasion in melanoma by suppressing chemokines and limiting CD8+ T cell infiltration." (PMID 41441975, 2025). "In contrast, no apparent association was observed between SEPHS1 expression and immunotherapy response in melanoma cohorts." (PMID 41441975, 2025). "In melanoma, SEPHS1 promotes immune exclusion and correlates with MDSC infiltration." (PMID 41441975, 2025). "In this study, we demonstrate that SEPHS1 suppresses CXCL9 and CXCL10 expression, impairs CD8+ T cell infiltration, and promotes immune evasion in melanoma." (PMID 41441975, 2025). "To evaluate the in vivo effects of Sephs1 knockdown on tumor growth and immunotherapy response, we established a subcutaneous B16F10 melanoma model in C57BL/6 J mice, followed by anti-PD-1 treatment." (PMID 41441975, 2025). "Multiplex immunofluorescence analysis of human melanoma tissues revealed that SEPHS1 was primarily localized in tumor cell cytoplasm and absent in stromal or immune cells." (PMID 41441975, 2025).
Miscarriage (1 paper, 2021). A pregnancy that ends at a stage in which the fetus is incapable of surviving on its own, defined as the spontaneous loss of a fetus before the 22th week of pregnancy. "Our results provide evidence that SEPHS1-deficiency is one of the contributors of natural miscarriages, and that the levels of SEPHS1 can be used as a marker for diagnosis or prognosis of natural miscarriages." (PMID 34769078, 2021).
pancreatic ductal adenocarcinoma (1 paper, 2025). An infiltrating adenocarcinoma that arises from the epithelial cells of the pancreas. "Except for pancreatic ductal adenocarcinoma, SEPHS1 expression was negatively correlated with Immune Score and ESTIMATE Score across the remaining 30 cancer types, and also showed significant negative correlations with Stromal Score in the majority of tumors." (PMID 41441975, 2025).
schizophrenia (1 paper, 2023). A major psychotic disorder characterized by abnormalities in the perception or expression of reality. "Both expressed in glial cells, MTMR10 is in a locus associated with schizophrenia and dendritic growth deficiency, substance use disorders and related behavioral traits, while SEPHS1 deregulation has been reported in rats under chronic stress." (PMID 37216417, 2023).
skin cutaneous melanoma (1 paper, 2025). "For instance, in skin cutaneous melanoma, the Spearman correlation coefficient between SEPHS1 promoter methylation and mRNA expression was − 0.33 (p = 1.34e−13), suggesting transcriptional repression by hypermethylation." (PMID 41441975, 2025).
cancer (6 papers, 2019 to 2025). A tumor composed of atypical neoplastic, often pleomorphic cells that invade other tissues. "Correlation analysis revealed that SEPHS1 expression was broadly and positively associated with regulators of seven major RNA modification types across multiple cancers." (PMID 41441975, 2025). "SEPHS1 expression was significantly associated with survival outcomes, and high SEPHS1 levels correlated with poor prognosis in several cancer types." (PMID 41441975, 2025). "TIMER analysis showed that SEPHS1 expression was positively associated with MDSCs infiltration across most cancers, suggesting a role in promoting immunosuppressive cell recruitment." (PMID 41441975, 2025). "In our previous study, SEPHS1 deficiency was shown to inhibit cell growth and malignancy in F9 cancer cells." (PMID 34769076, 2021). "To assess the association between SEPHS1 mRNA expression and patient prognosis, we performed Kaplan–Meier survival analyses combined with log-rank tests and univariate Cox regression models across multiple cancer types." (PMID 41441975, 2025). "Targeting SEPHS1 restores immune activity and potentiates immune checkpoint blockade, suggesting a novel immunometabolic strategy to enhance cancer immunotherapy." (PMID 41441975, 2025). "Together, these findings indicate that SEPHS1 expression is regulated by both DNA methylation and RNA modifications in a cancer type-specific manner." (PMID 41441975, 2025). "To investigate the expression profile of SEPHS1 across cancers, we first analyzed RNA-seq data from 1019 human cancer cell lines obtained from the CCLE." (PMID 41441975, 2025). "SEPHS1 expression was positively correlated with multiple proliferation-related pathways in over 80% of cancer types." (PMID 41441975, 2025). "Annotation of SEPHS1 methylation probes revealed that promoter methylation was significantly negatively correlated with SEPHS1 mRNA expression in most cancer types." (PMID 41441975, 2025). "To validate the biological relevance of SEPHS1 in specific cancer types, we selected B16F10 and MB49 cell lines as models for SKCM and BLCA, respectively." (PMID 41441975, 2025). "Collectively, these findings suggest that SEPHS1 contributes to tumor cell proliferation and partially supports migratory and invasive phenotypes, reinforcing its potential role in cancer progression." (PMID 41441975, 2025). "This study systematically characterized the expression heterogeneity and epigenetic regulation of selenium metabolism-related genes across cancers, with a particular focus on SEPHS1." (PMID 41441975, 2025). "Integrating pan-cancer, CRISPR, and immunotherapy cohort analyses, we identify SEPHS1 as a selenium metabolism-associated gene implicated in tumor immune regulation." (PMID 41441975, 2025). "We next evaluated SEPHS1 mRNA expression in tumor versus adjacent normal tissues across TCGA cancer types." (PMID 41441975, 2025). "SEPHS1 was significantly upregulated in tumor tissues compared to normal tissues in most cancer types, suggesting a broad role in tumorigenesis." (PMID 41441975, 2025). "Initially, we explored the correlation between CNV and mRNA expression in 14 RMS model-associated genes in 33 kinds of tumors and revealed that CHMP7 expression was significantly modulated by CNV in almost all cancers, followed by SEPHS1 and AASDHPPT." (PMID 37124622, 2023). "Since 2H11 is a commonly used cancer cell line derived from mouse endothelial cells, we chose 2H11 to investigate the function of SEPHS1 in endothelial cells." (PMID 34769076, 2021). "Since TGF-β-induced EMT promotes cancer cell migration and invasion, we then detected the effects of SEPHS1 on TGF-β-induced HCC cells migration and invasion." (PMID 33622411, 2021). "The consistent positive correlations across cancer types imply that RNA modification networks may cooperatively contribute to SEPHS1 upregulation in tumor cells." (PMID 41441975, 2025).
cancer (continued). "A better understanding of the functions of SEPHS1 in different types of human cancer may provide more insights into cancer progression." (PMID 33622411, 2021). "Interestingly, SEPHS1 appears to exert distinct immune effects in different cancer types." (PMID 41441975, 2025). "In both human and murine cancer cell lines, marker-based CRISPR screening showed that SEPHS1/Sephs1 knockout significantly increased MHC-I expression, suggesting enhanced tumor immunogenicity." (PMID 41441975, 2025). "Consistent with the promotion of cancer cells migration and invasion by TGF-β/SMAD signaling, SEPHS1 promotes HCC cell migration and invasion." (PMID 33622411, 2021). "Nevertheless, the contribution of SEPHS1 to cancer progression and immune regulation has not been systematically studied." (PMID 41441975, 2025).
tumor (3 papers, 2021 to 2025). "Beyond tumor biology, SEPHS1 encodes a key rate-limiting enzyme in selenium metabolism and plays an essential role in maintaining redox balance." (PMID 41441975, 2025). "In co-culture models using tumor cells and T cells, sgRNAs targeting SEPHS1/Sephs1 were enriched in negatively selected populations, indicating that SEPHS1 loss sensitized tumor cells to T cell-mediated killing." (PMID 41441975, 2025). "To investigate the role of SEPHS1 in tumor immunity, we analyzed its association with immune microenvironment features." (PMID 41441975, 2025). "Furthermore, in vivo CRISPR screens under various immune contexts revealed that Sephs1-deficient tumor cells were negatively selected, implying decreased fitness under immune pressure." (PMID 41441975, 2025). "Since angiogenesis is the most prominent feature of tumor growth, and since we have previously shown that SEPHS1 deficiency inhibits tumor-cell malignancy, targeted removal of SEPHS1 in endothelial cells may provide a potential new measure for antitumor therapy." (PMID 34769076, 2021). "SEPHS1 was highly expressed in epithelial and endothelial cells across multiple tumor types, with malignant epithelial cells showing higher expression than their normal counterparts." (PMID 41441975, 2025). "Compared to controls, Sephs1 knockdown significantly reduced tumor volume and weight by day 15 post-implantation." (PMID 41441975, 2025). "To investigate the relationship between SEPHS1 expression and tumor cell phenotypes, we performed pathway enrichment analysis using HALLMARK gene sets." (PMID 41441975, 2025). "Multi-omics analyses revealed consistently elevated expression of AHCY, BUD23, LCMT1, MARS1, METTL6, SCLY and SEPHS1 in various tumor types." (PMID 41441975, 2025). "Future studies should aim to establish SEPHS1-centered regulatory networks using multi-omics approaches and expand validation across various tumor types and immune contexts." (PMID 41441975, 2025). "Genetic silencing of SEPHS1 not only impairs tumor cell growth but also promotes T cell infiltration and effector function, ultimately enhancing the efficacy of anti–PD-1 therapy in vivo." (PMID 41441975, 2025). "In vivo, subcutaneous transplantation of MB49-shSephs1 cells into C57BL/6 J mice demonstrated that Sephs1 knockdown markedly reduced tumor growth, as indicated by slower tumor progression and smaller tumor volume compared to control." (PMID 41441975, 2025). "Therefore, evaluating SEPHS1 function across tumor immune subtypes and identifying predictive biomarkers such as PD-L1, TMB, or selenium status will be crucial." (PMID 41441975, 2025). "The combination of Sephs1 knockdown and anti-PD-1 therapy resulted in further tumor suppression." (PMID 41441975, 2025). "Regions with high SEPHS1 expression showed reduced CD8+ T cell infiltration, forming an “immune-excluded” phenotype, whereas low SEPHS1 expression was associated with increased CD8+ T cell infiltration and direct tumor contact." (PMID 41441975, 2025). "SEPHS1 was also detectable in fibroblasts and immune cell subsets, particularly in proliferating T cells and monocyte/macrophage populations, suggesting potential involvement in immune regulation within the tumor microenvironment." (PMID 41441975, 2025). "From a translational perspective, SEPHS1 may function as a context-dependent metabolic regulator that links selenium metabolism to tumor immunity." (PMID 41441975, 2025). "Specifically, we demonstrate that SEPHS1 shapes the tumor immune landscape and modulates the efficacy of anti-PD-1 therapy, thereby providing mechanistic insight into its prognostic relevance and tumor-type specificity." (PMID 41441975, 2025). "To explore SEPHS1 expression at the single-cell level, we analyzed data from TISCH, a tumor immune single-cell RNA-seq database." (PMID 41441975, 2025). "In the absence of T cells, Sephs1 knockdown led to a mild reduction in tumor cell viability." (PMID 41441975, 2025).
SEPHS1 also shares sentences with these, for which no sentence is quoted: breast carcinoma (3 papers); Anxiety (1); chronic lymphocytic leukemia (1); chronic myeloid leukemia (1); depression (1); endometrial carcinoma (1); glioblastoma (1); glioma (1); hematological malignancies (1); infection (1); invasive breast carcinoma (1); lung adenocarcinoma (1); neuroblastoma (1); ovarian carcinoma (1); renal carcinoma (1); selenium deficiency (1); uterine corpus endometrial carcinoma (1).